RNU6-78P (RNA, U6 small nuclear 78, pseudogene)
Synonyms: RNU6-78
Gene: Small nuclear RNA gene on chromosome 13 (25,517,119 to 25,517,225, forward strand). Ensembl gene ENSG00000199767.
Homologues: Orthologues: chimpanzee U6 (100% identical), macaque U6 (88% identical), dog U6 (76% identical), pig U6 (71% identical), pig U6 (65% identical), dog U6 (64% identical). Paralogues in human: RNU6-266P (86% identical), RNU6-19P (85% identical), RNU6-21P (85% identical), RNU6-61P (85% identical), RNU6-1 (84% identical), RNU6-15P (84% identical), RNU6-166P (84% identical), RNU6-188P (84% identical), RNU6-2 (84% identical), RNU6-214P (84% identical), RNU6-28P (84% identical), RNU6-35P (84% identical), and 1286 more.